KANK1 (KN motif and ankyrin repeat domains 1)
Description:
Adapter protein that links structural and signaling protein complexes positioned to guide microtubule and actin cytoskeleton dynamics during cell morphogenesis. At focal adhesions (FAs) rims, organizes cortical microtubule stabilizing complexes (CMSCs) and directly interacts with major FA component TLN1, forming macromolecular assemblies positioned to control microtubule-actin crosstalk at the cell edge. Recruits KIF21A in CMSCs at axonal growth cones and regulates axon guidance by suppressing microtubule growth without inducing microtubule disassembly once it reaches the cell cortex. Interacts with ARFGEF1 and participates in establishing microtubule-organizing center (MTOC) orientation and directed cell movement in wound healing. Regulates actin stress fiber formation and cell migration by inhibiting RHOA activation in response to growth factors; this function involves phosphorylation through PI3K/Akt signaling and may depend on the competitive interaction with 14-3-3 adapter proteins to sequester them from active complexes. Inhibits the formation of lamellipodia but not of filopodia; this function may depend on the competitive interaction with BAIAP2 to block its association with activated RAC1. Inhibits fibronectin-mediated cell spreading; this function is partially mediated by BAIAP2. In the nucleus, is involved in beta-catenin-dependent activation of transcription. During cell division, may regulate DAAM1-dependent RHOA activation that signals centrosome maturation and chromosomal segregation. May also be involved in contractile ring formation during cytokinesis (By similarity). Potential tumor suppressor for renal cell carcinoma (Probable).
Synonyms: ANKRD15; KANK; KIAA0172; CPSQ2
Tractability: Antibody: UniProt places it where antibodies can reach, with high confidence; its Gene Ontology location is reachable by antibodies, with high confidence; the Human Protein Atlas places it where antibodies can reach. PROTAC: ubiquitination databases record sites on it; its protein half-life has been measured.
Gene: Protein-coding gene on chromosome 9 (470,291 to 746,105, forward strand). Ensembl gene ENSG00000107104.
Subcellular location: Cytoplasm, cell cortex; Cell projection, ruffle membrane; Cytoplasm; Nucleus; Cytoplasm (Isoform 1); Cytoplasm (Isoform 2)
Subcellular location (Human Protein Atlas): Plasma membrane
Pathways (Reactome):
Disease: Signaling by membrane-tethered fusions of PDGFRA or PDGFRB
Signal Transduction: Estrogen-dependent gene expression
Gene Ontology:
Molecular function: beta-catenin binding; protein binding; protein-macromolecule adaptor activity
Biological process: actin cytoskeleton organization; cell population proliferation; cortical microtubule organization; negative regulation of actin filament polymerization; negative regulation of cell migration; negative regulation of insulin receptor signaling pathway; negative regulation of lamellipodium morphogenesis; negative regulation of neuron projection development; negative regulation of Rho protein signal transduction; negative regulation of ruffle assembly; negative regulation of substrate adhesion-dependent cell spreading; podocyte cell migration; positive regulation of canonical Wnt signaling pathway; positive regulation of Wnt signaling pathway; positive regulation of wound healing; regulation of establishment of cell polarity; regulation of Rho protein signal transduction; establishment or maintenance of cell polarity
Cellular component: cell cortex; cytoplasm; nucleus; plasma membrane; ruffle membrane; cytoskeleton; microtubule associated complex
Genetic constraint (gnomAD): Loss-of-function variants: 101 observed, 103.67 expected, observed/expected ratio (o/e) 0.97, 90% interval 0.83 to 1.15. The synonymous counts are far from expectation, so gnomAD's model fits this gene poorly and the ratio says little. Missense variants: 2,297 observed, 1,722.5 expected, observed/expected ratio (o/e) 1.33, 90% interval 1.29 to 1.38. Synonymous variants: 839 observed, 664.11 expected, observed/expected ratio (o/e) 1.26, 90% interval 1.19 to 1.34.
Homologues: Orthologues: chimpanzee KANK1 (98% identical), macaque KANK1 (96% identical), pig KANK1 (89% identical), guinea pig KANK1 (87% identical), rabbit KANK1 (86% identical), mouse Kank1 (85% identical), rat Kank1 (84% identical), tropical clawed frog kank1 (59% identical), zebrafish kank1a (55% identical), zebrafish kank1b (34% identical), zebrafish kank3 (26% identical), Drosophila melanogaster Kank (21% identical), and 1 more. Paralogues in human: KANK2 (24% identical), KANK4 (23% identical), KANK3 (21% identical).
Diseases named in the same sentence as KANK1 in open-access papers:
KANK1 is named in the same sentence as 67 diseases in open-access papers, as found by Europe PMC text mining. Sharing a sentence is not in itself a finding about the gene and the disease. The quoted sentences say what the papers report.
cerebral palsy (7 papers, 2012 to 2024). A group of disorders affecting the development of movement and posture, often accompanied by disturbances of sensation, perception, cognition, and behavior. "KANK1 is reported to be associated with cerebral palsy, and many CP cases are also usually reported to have autism and other NDD." (PMID 34802461, 2021). "Previous studies have identified mutations in the actin-capping protein KANK1 and the adaptor protein-4 complex in forms of inherited cerebral palsy, suggesting a role for components of the dynamic cytoskeleton in the genesis of the disease." (PMID 23836506, 2013). "Deletions within the paternal KANK1 gene have been identified in several children with cerebral palsy." (PMID 22768875, 2012). "Using a curated list of 484 genes directly implicated in ID (ID Project, University of Colorado Denver) we found two genes: KN Motif And Ankyrin Repeat Domains 1 (KANK1), associated with cerebral palsy, and Transcription factor 4 (TCF4), associated with Pitt-Hopkins Syndrome." (PMID 31288860, 2019).
renal cell carcinoma (7 papers, 2011 to 2024). "KANK1 (KN motif and ankyrin repeat domains 1) was first described in renal cell carcinomas where it was identified as a tumor suppressor." (PMID 36005139, 2022). "Kank1 was initially reported to suppress the growth of renal cell carcinomas by arresting the cell cycle in the G0/G1 phase, which suggested Kank1 as a mediator of cell proliferation and apoptosis." (PMID 35805114, 2022). "Except known as a gene for cerebral palsy spastic quadriplegia type 218, KANK1 has been reported as a candidate TSG in renal cell carcinoma patients, as it was found that KANK1 re-expression was able to inhibit HEK293 cell growth by reducing proliferation." (PMID 28067315, 2017). "The human Kank1 gene (KANK1) was found as a candidate tumor suppressor gene for renal cell carcinoma." (PMID 29036929, 2017).
gastric cancer (4 papers, 2017 to 2022). A primary or metastatic malignant neoplasm involving the stomach. "The identification of the circCASP9/miR-589-5p/KANK1 regulatory axis will help to elucidate the mechanisms underlying the occurrence and development of gastric cancer." (PMID 35320976, 2022). "Moreover, KANK1 deletions and mutations (missense, nonsense, and frameshift mutations) are also frequent in prostate, lymphoid, pancreatic, uterine, and stomach cancers." (PMID 28067315, 2017). "Further, in vivo and in vitro studies confirm that KANK1 upregulation in gastric cancer leads to a decrease in the metastatic ability of tumour cells." (PMID 31679074, 2020). "In addition, Kank1 is a documented tumor suppressor gene that inhibits the proliferation, migration, and invasion of tumor cells (gastric cancer, lung cancer, etc.)and promotes their apoptosis." (PMID 34917045, 2021).
melanoma (4 papers, 2020 to 2025). A malignant, usually aggressive tumor composed of atypical, neoplastic melanocytes. "In melanoma, liprin β1 was found to be overexpressed and its expression strongly correlated with the expression of KANK1 and KANK2." (PMID 32195252, 2020).
nephrotic syndrome (4 papers, 2023 to 2024). A collection of symptoms that include severe edema, proteinuria, and hypoalbuminemia; it is indicative of renal dysfunction. "Recent research has linked the KANK1 gene with nephrotic syndrome." (PMID 38891998, 2024). "Given the results presented in our study and those published in the literature, individuals with nephrotic syndrome may have pathogenic variants in KIF21A, encoding a direct interaction partner of KANK1 and KANK2." (PMID 37932480, 2023). "For instance, KANK1 and CRB2, initially identified by our lab in one and four families respectively, have now been reported in seven and thirty-one families in Human Gene Mutation Database, indicating the evolving landscape of genetic discoveries in nephrotic syndrome." (PMID 38659911, 2024).
invasive breast carcinoma (3 papers, 2020 to 2024). A carcinoma that infiltrates the breast parenchyma. "KANK1 is associated with improved prognosis among patients with invasive breast cancer." (PMID 39850493, 2024). "Low KANK1 expression in tumor tissues was associated with a poor prognosis in oral squamous cell carcinoma (OSCC), astrocytoma, and lung adenocarcinoma patients, while KANK1 overexpression indicated a good prognosis in patients with invasive breast cancer." (PMID 35559038, 2022). "KANK1 is involved in progression of a variety of solid tumours; however, its role in invasive breast cancer (BC) remains unknown." (PMID 31679074, 2020).
osteosarcoma (3 papers, 2021 to 2023). A usually aggressive malignant bone-forming mesenchymal neoplasm, predominantly affecting adolescents and young adults. "To get further insight into the mechanisms underlying the tumor-promoting roles of TRAIP in osteosarcoma, we performed mass spectrometry and identified KANK1 as a TRAIP substrate." (PMID 34349117, 2021). "Interestingly, high KANK1 levels were associated with prolonged metastasis-free survival (P = 0.021) and overall survival (P = 0.025) in patients with osteosarcoma." (PMID 34349117, 2021). "KANK1 silencing increased osteosarcoma cell proliferation, whereas KANK1 overexpression inhibited osteosarcoma cell growth." (PMID 34349117, 2021). "We found that there was a relatively weak correlation between TRAIP and KANK1 in osteosarcoma tissues (Spearman r = −0.2516, P = 0.0485)." (PMID 34349117, 2021). "We also investigated the protein of levels of TRAIP and KANK1 in a tissue microarray of osteosarcoma specimens (n = 70)." (PMID 34349117, 2021). "To evaluate the relevance of KANK1 in TRAIP’s ability to promote osteosarcoma progression, we generated osteosarcoma cells with stable knockdown of TRAIP, KANK1, and the combination of the two." (PMID 34349117, 2021). "To explore the role of KANK1 in osteosarcoma, we evaluated its expression levels in osteosarcoma tissues." (PMID 34349117, 2021). "To further explore the tumor-suppressive roles of KANK1 in osteosarcoma, we performed RNA sequencing (RNA-seq) analysis after silencing KANK1 in MNNG/HOS cells." (PMID 34349117, 2021). "In addition, TRAIP-mediated downregulation of KANK1 can enhance the invasion and proliferation of osteosarcoma cells through the IGFBP3/AKT pathway." (PMID 35320976, 2022). "We also found that TRAIP regulated IGFBP3 expression through KANK1 in osteosarcoma cells." (PMID 34349117, 2021). "We also found that KANK1 downregulated IGFBP3 in osteosarcoma cells." (PMID 34349117, 2021). "Thus, the KANK1/IGFBP3/AKT pathway is crucial for understanding the specific mechanism of the progression of osteosarcoma." (PMID 34349117, 2021). "TRAIP enhances osteosarcoma invasion and proliferation through the modulation of IGFBP3/AKT by promoting the degradation of KANK1, which is a tumor suppressor." (PMID 36999051, 2023). "Conversely, KANK1 overexpression upregulated IGFBP3 and reduced AKT phosphorylation levels in osteosarcoma cells." (PMID 34349117, 2021). "We identified KANK1 as a TRAIP binding partner, which was verified by co-immunoprecipitation in osteosarcoma cells and GST-pull down." (PMID 34349117, 2021). "Notably, TRAIP activated the AKT pathway by promoting KANK1 polyubiquitination and degradation and downregulating IGFBP3 in osteosarcoma cells." (PMID 34349117, 2021). "TRAIP knockdown resulted in increased KANK1protein levels but did not affect KANK1 mRNA levels in any of the three osteosarcoma cell lines." (PMID 34349117, 2021). "In addition, we found that TRAIP promoted KANK1 polyubiquitination and subsequent degradation, downregulating IGFBP3 and activating the AKT pathway in osteosarcoma cells." (PMID 34349117, 2021). "Interestingly, we found that KANK1 was downregulated in osteosarcoma tissues compared with non-malignant tissues." (PMID 34349117, 2021).
Alzheimer disease (2 papers, 2020 to 2021). A progressive, neurodegenerative disease characterized by loss of function and death of nerve cells in several areas of the brain leading to loss of cognitive function such as memory and language. "Examples of known human genes associated with memory also identified in our study include: NTM and KLHl20 that are associated with Alzheimer’s disease and DOCK8 and KANK1 that are associated with neurodevelopmental disorders including memory potential." (PMID 32299497, 2020).
autism (2 papers, 2021 to 2023). Persistent deficits in social interaction and communication and interaction as well as a markedly restricted repertoire of activity and interest as well as repetitive patterns of behavior. "We have identified additional 2 de novo LOF variants, 14 LOFs with unknown inheritance and 4 de novo missense from 11 ASD cases for KANK1 from other autism genetic research laboratory data (including MSSNG database)." (PMID 34802461, 2021).
autism spectrum disorder (2 papers, 2021 to 2022). A spectrum of developmental disorders that includes autism, and Asperger syndrome. "Genetic duplications of 9p24.3, and therefore the DOCK8 and KANK1 genes, are associated with autism spectrum disorders (ASD), intellectual disability/developmental delay (ID/DD), attention deficit hyperactivity disorder (ADHD), epilepsy, learning problems, and language disorders." (PMID 33455084, 2021). "Recent studies suggest that duplication of the 9p24.3 chromosomal locus, which includes the DOCK8 and KANK1 genes, is associated with autism spectrum disorders (ASD), intellectual disability/developmental delay (ID/DD), learning problems, language disorders, hyperactivity, and epilepsy." (PMID 33455084, 2021). "For example, Slc1a2, Prdm16, Kank1 and Ddah1 were target genes of Dbx2, the high expression of Slc1a2 was found to reduce the risk for PD in a Chinese cohort and the other genes are associated with cognitive function, autism spectrum disorder and depression-like behavior, respectively." (PMID 36142685, 2022). "We describe three unrelated patients with autism spectrum disorders and intellectual disabilities / developmental delay who are carriers of the 9p24.3 duplication including DOCK8 and KANK1." (PMID 33455084, 2021).
breast carcinoma (2 papers, 2020 to 2024). "The results of the in silico analysis points to an oncogenic role of KANK1 in breast cancer, which is in sharp contrast to the proposed tumor suppressor function of KANK1 observed with in cellulo studies." (PMID 39613731, 2024). "Next, we performed a series of experiments to confirm the relevance of our findings from the KANK1-WTPyMT mouse breast cancer model for human breast cancer." (PMID 39613731, 2024). "When we induced breast cancer with the PyMT transgene, we found that KANK1-WTPyMT suffered from a significantly higher tumor incidence and tumor load than their KANK1-KOPyMT littermates." (PMID 39613731, 2024). "Next, we used the KANK1-KO mouse strain to assess the tumor function of KANK1 in a breast cancer model." (PMID 39613731, 2024). "Our findings show that the recruitment of KANK1 to cell-cell junctions in breast cancer cells of KANK1-WTPyMT mice is a stepwise process." (PMID 39613731, 2024). "Based on this finding, we decided to resolve this contradiction by defining and characterizing the tumor activity of KANK1 in breast cancer using different model systems." (PMID 39613731, 2024). "Here, we address this discrepancy and report that KANK1 promotes proliferation and survival of PyMT-transformed mammary tumor cells in vivo." (PMID 39613731, 2024). "Finally, the LEC polarity in active mammary glands, the gland morphology in pregnancy, lactation, and involution as well as the offspring numbers were normal in KANK1-null females, indicating that mammary glands were unaltered prior to breast cancer induction." (PMID 39613731, 2024). "Stratification of the TCGA breast cancer cohort based on their molecular characteristics revealed that poor prognosis correlates with high KANK1 mRNA and protein levels in all subtypes, irrespective whether they are ER+ or of luminal subtype A or B." (PMID 39613731, 2024). "Here the authors find that KANK1 competes with the polarity protein Scribble at cell-cell junctions for NOS1AP binding, leading to TAZ stabilization and activation, and breast cancer progression." (PMID 39613731, 2024). "In light of this complex molecular choreography, and its important role for breast cancer, it will be important to biochemically and structurally determine the binding characteristics of SCRIB, NOS1AP and KANK1 in future." (PMID 39613731, 2024). "Second, colocalization of KANK1, NOS1APc and cadherin were observed at cell-cell junctions and TAZ in the nucleus of human breast cancer cells." (PMID 39613731, 2024). "First, we found that KANK1 expression was restricted to epithelial tumor cells and absent from the surrounding stroma in samples of luminal breast cancers." (PMID 39613731, 2024). "We favored breast cancer for our studies because Kaplan-Meier survival analysis of the TCGA breast cancer cohort revealed that high, rather than the expected low KANK1 expression correlates with a poor survival rate of breast cancer patients." (PMID 39613731, 2024). "High KANK1 protein expression was correlated with smaller tumour size and HER2 negativity, and better outcome in terms of longer breast cancer-specific survival [p = 0.013, HR 0.7, 95% CI 0.536–0.893] and time to distant metastasis [p = 0.033, HR 0.65, 95% CI 0.51–0.819]." (PMID 31679074, 2020). "Since it is not entirely clear whether KANK1 promotes or curbs tumor development in vivo, we decided to analyze breast cancer growth in mice and tumoroids lacking KANK1 expression." (PMID 39613731, 2024). "Immunostaining of tumor sections from human breast cancer patients revealed that the majority of tumor cells contained KANK1 at cell-cell junctions and TAZ in the nucleus, and those LECs still attached to the BMs contained KANK1 at their basal, BM-binding side and TAZ diffusely in the cytoplasm." (PMID 39613731, 2024).
breast carcinoma (continued). "Importantly, the same KANK1-regulated TAZ signaling described here for transformed luminal epithelial cells (LECs) in mice is also operating in the human breast cancer cell line MCF7 transplanted into immunocompromised mice and in human breast cancer." (PMID 39613731, 2024).
colorectal cancer (2 papers, 2020 to 2022). A primary or metastatic malignant neoplasm that affects the colon or rectum. "KANK1 has also been reported as a target for circRNA-sponge mechanisms; for example, circDDX17 reduces 5-fluorouracil resistance and hinders tumorigenesis in colorectal cancer by regulating the miR-31-5p/KANK1 axis." (PMID 35559038, 2022).
glioma (2 papers, 2017 to 2022). A benign or malignant brain and spinal cord tumor that arises from glial cells (astrocytes, oligodendrocytes, ependymal cells). "The other NTRK2 fused glioma (KANK1:NTRK2), originally diagnosed as ependymoma, was classified as pleomorphic xanthoastrocytoma (PXA) (CS 0.90)." (PMID 36163281, 2022).
Intellectual disability (2 papers, 2017 to 2021). "In the DECIPHER dataset, 16 subjects with intellectual disability carry DOCK8 duplications/gains and ten carry KANK1 duplications/gains." (PMID 29191242, 2017).